CFTR (CF transmembrane conductance regulator)
Diseases named in the same sentence as CFTR in open-access papers (continued):
Sharing a sentence is not in itself a finding about the gene and the disease.
cystic fibrosis (continued). "For example, deep intronic CFTR variants that introduce pseudoexons or disrupt normal splicing were later found to be present in a significant percentage of patients with suspected cystic fibrosis but negative WES results." (PMID 41614802, 2025). "Defects in the CFTR protein synthesis and malfunction of the CFTR protein lead to a common monogenic autosomal recessive disorder, cystic fibrosis, and CFTR-related disorders such as congenital bilateral aplasia of the vas deferens (CBAVD), bronchiectasis, and chronic pancreatitis." (PMID 40724872, 2025). "Cystic fibrosis is an autosomal recessive disorder characterized by impaired function of the CF transmembrane conductance regulator (CFTR) protein, which serves as a chloride channel in epithelial cells of the lungs, sweat glands, liver, pancreas, and intestines." (PMID 40046358, 2025). "The enhanced accuracy and reliability of CFTR_TLnot only contribute to a deeper molecular understanding of CFTR-relatedpathologies but also hold promising implications for the developmentof targeted therapeutics aimed at restoring CFTR function in cysticfibrosis patients." (PMID 41358137, 2025). "In both cases, the team concluded that two flavonoids might have potential use for the treatment of CFTR‐related diseases like cystic fibrosis and bronchiectasis." (PMID 41070403, 2025). "Cystic fibrosis is an inherited genetic disease caused by the following clinical/biochemical features: (a) dysregulation of the cystic fibrosis transmembrane regulator (CFTR) gene, (b) a chronic hyperinflammatory state and (c) frequent and severe bacterial infections of the lungs." (PMID 41226119, 2025). "On 20 December 2024, the U.S. FDA approved Alyftrek (vanzacaftor/tezacaftor/deutivacaftor), a next-generation combination of CFTR modulators developed by Vertex Pharmaceuticals for cystic fibrosis patients aged 6 years and older with at least one F508del mutation or other responsive mutations." (PMID 40430547, 2025). "However, CF-NBS also results in cases where the diagnosis remains uncertain, categorized as Cystic Fibrosis Screen Positive Inconclusive Diagnosis/CFTR-related Metabolic Syndrome (CFSPID/CRMS), posing a significant clinical challenge." (PMID 40700044, 2025). "Similarly, a study focusing on cystic fibrosis treatment found that a dosage of 0.1 mg/kg/day for two consecutive days was sufficient to restore the function of the CFTR gene in CFTR-knockout mice." (PMID 40621603, 2025). "CFTR modulator therapy has introduced a new era in the treatment of cystic fibrosis." (PMID 41007135, 2025). "Patients with cystic fibrosis who are non-responsive to treatments due to specific mutations need alternative CF transmembrane conductance regulator (CFTR)-independent therapies." (PMID 40926414, 2025). "CFTR, a unique member of the ATP-binding cassette (ABC) transporter superfamily, is best known for the ΔF508 deletion mutation, which disrupts protein folding and trafficking, leading to cystic fibrosis." (PMID 41155636, 2025). "Here, in a clinical trial, the authors show that CFTR-modulator therapy reshapes the lung and gut microbiomes in cystic fibrosis, reducing bacteria such as Staphylococcus in the lungs and Escherichia in stool, and showing that microbiome dysbiosis can be partially reversed." (PMID 41253756, 2025). "Heterozygous carriers of CFTR mutations do not develop cystic fibrosis but have an increased risk for pancreatitis." (PMID 39996177, 2025). "These RFFL-targeting ASOs enhanced CFTR modulator efficacy by increasing functional CFTR in patient-derived bronchial epithelial cells, offering a promising nucleic acid-based therapeutic strategy for cystic fibrosis beyond current modulators." (PMID 41323797, 2025). "Unlike cystic fibrosis, where a single variant (CFTR-ΔF508) accounts for approximately 70% of patients, LQTS-causing Kv11.1 variants are distributed throughout the channel." (PMID 41026531, 2025).
cystic fibrosis (continued). "There are hypotheses from the pre-CFTR modulator era regarding how CFTR expression in the kidneys may enhance renal clearance in individuals with cystic fibrosis (pwCF)." (PMID 39655913, 2025). "In addition to their pharmacological benefits, CFTR modulators are also being investigated for their impact on microbial and functional lung issues in cystic fibrosis patients." (PMID 39996840, 2025). "Regarding the role of S100A10 in fibrogenesis, nothing is known, except that its interaction with CFTR could play a role in lung fibrosis upon cystic fibrosis." (PMID 40841353, 2025). "CFTR-null/ΔF508 pigs likewise show hypomineralized crowns on backscattered-electron imaging, mirroring the higher prevalence of developmental enamel defects reported in cystic fibrosis." (PMID 41294875, 2025). "Lumacaftor-ivacaftorin patients with cystic fibrosis homozygous for Phe508del CFTR.N Engl J Med." (PMID 40297296, 2025). "These processes are fairly simple relative to those that coordinate the assembly of the cystic fibrosis transmembrane conductance regulator ion channel (CFTR), a target for leading cystic fibrosis drugs that is cotranslationally folded into ER membranes while interacting with dozens of QC proteins." (PMID 40553789, 2025). "Improvements in CFTR function compared with baseline elexacaftor–tezacaftor–ivacaftor values demonstrate the potential opportunity to restore normal physiology early and prevent development or progression of cystic fibrosis." (PMID 39756425, 2025). "Cystic Fibrosis is primarily diagnosed in Germany through newborn screening (NS) using immunoreactive trypsinogen (IRT)/Pancreatitis-Associated Protein (PAP) measurements and genetic testing for common CFTR gene variants." (PMID 41399729, 2025). "Bessonova L., Volkova N., Higgins M., Bengtsson L., Tian S., SimardC., Konstan M.W., Sawicki G.S., Sewall A., Nyangoma S.,Elbert A., Marshall B.C., Bilton D. Data from the US and UK cysticfibrosis registries support disease modification by CFTR modulationwith ivacaftor." (PMID 40297296, 2025). "The search employed a combination of key terms such as “CFTR modulators”, “CFTR binding sites”, “potentiators”, “correctors”, and “therapeutic strategies in cystic fibrosis”, and covered the period from 1989 to the present to ensure the inclusion of the most up-to-date and relevant information." (PMID 39996840, 2025). "Together, these reports demonstrate that arsenic impairs CFTR function and support the hypothesis that there is a shared mechanism driving both cystic fibrosis and arsenic-induced lung disease." (PMID 40333927, 2025). "The advent of CFTR modulators represents a landmark advancement in cystic fibrosis therapy." (PMID 40842499, 2025). "We previously published pioneering data that underscored a substantial change in the impact of Aspergillus-related diseases in patients with cystic fibrosis (pwCF) treated with a combination of cystic fibrosis transmembrane conductance regulator (CFTR) modulators, so-called Trikafta." (PMID 40736245, 2025). "The mechanisms for Mab susceptibility in CF patients are exacerbated by hyper-inflammation, the presence of a thickened mucus membrane, and ciliary dysfunction that primarily result from mutations in the Cystic Fibrosis Transmembrane Conductance Regulator (CFTR) gene." (PMID 40415550, 2025). "Important guidelines for newborn screening and care of infants diagnosed with CF transmembrane conductance regulator (CFTR)‐Related Metabolic Syndrome/Cystic Fibrosis Screen Positive Inconclusive Diagnosis (CRMS/CFSPID) were published alongside related key lessons from individual programs." (PMID 40778614, 2025). "ARN23765 is a CFTR corrector molecule developed as part of the Task Force for Cystic Fibrosis (TFCF) project, a strategic initiative funded by the Fondazione Italiana per la Ricerca in Fibrosi Cistica (FFC) in collaboration with the Istituto Italiano di Tecnologia (IIT)." (PMID 39996840, 2025).
cystic fibrosis (continued). "Overall, the improvements in sweat chloride concentrations seen in both trials address the causal biology of cystic fibrosis and advance the field towards the goal of reaching normal levels of CFTR function seen in people without cystic fibrosis." (PMID 39756424, 2025). "More than 2000 pathogenic mutations have been reported to date in Cystic Fibrosis Transmembrane Regulator (CFTR) gene and this explains, at least partly, the clinical heterogeneity observed in people with Cystic Fibrosis (pwCF) and the atypical manifestations in CFTR-related disorders (CFTR-RD)." (PMID 40301948, 2025). "It is estimated that approximately 10% of people with cystic fibrosis carry mutations that do not currently benefit from CFTR modulators." (PMID 40282362, 2025). "Additionally, despite recent progress with CFTR modulators for cystic fibrosis, the continued development of new mucolytic, anti-inflammatory, and anti-infective therapies remains crucial, particularly for patients with advanced stages of lung disease." (PMID 39408877, 2024). "Detailed insights are provided into CFTR (ABCC7), an anion channel implicated in cystic fibrosis, and FPN1 (ferroportin 1/SLC40A1), the sole known iron exporter in humans, highlighting their unique roles as ion transporters within ABC and SLC transporter superfamilies." (PMID 39770445, 2024). "Furthermore, they have been associated with several diseases and pathological conditions, such as cystic fibrosis (ABCC7/CFTR) or drug resistance in the case of P-glycoprotein (P-gp)." (PMID 39590609, 2024). "In literature there are reports on the combined carriership of CFTR and SERPINA1 gene variants in case of a clinical picture of cystic fibrosis, though without homozygous carriership of CFTR gene variant." (PMID 39881831, 2024). "Compared to the common recommendation of screening for cystic fibrosis carrier status in Caucasians, our study revealed that only 0.97% of our sample carried pathogenic variants (PV) and likely pathogenic variants (LPV) in the CFTR gene." (PMID 38167091, 2024). "Additionally, the poly-SUMO2/3 modification of mutant CFTR protein associated with cystic fibrosis promotes its degradation, while SUMO1 conjugation enhances CFTR stability." (PMID 39431155, 2024). "Cystic fibrosis results from abnormalities in the CFTR protein." (PMID 39043981, 2024). "In addition, many genetic disorder diseases can also be recreated by organoids, such as cystic fibrosis featured with the defective transmembrane conductance regulator (CFTR) function." (PMID 38169573, 2024). "These mutations showed additive effects with other gain-of-function mutants and affected the sensitivity and response to potentiators, highlighting the critical role of the TMD2 region in regulating CFTR activity and its potential as a therapeutic target for cystic fibrosis." (PMID 39770445, 2024). "The screening of cystic fibrosis typically consists of a CFTR gene test." (PMID 38790500, 2024). "We show that germline testing detects a PV in 23.9% of subjects with AP or CP, including PRSS1 (4.5%) and biallelic CFTR (1.3%) which have direct implications for management (pancreatic cancer screening and cascade testing for PRSS1, testing for cystic fibrosis for biallelic CFTR)." (PMID 39172977, 2024). "CFTR is the causative gene for both cystic fibrosis and the congenital bilateral absence of the vas deferens." (PMID 39149602, 2024). "The impaired function of the CFTR channel causes cellular alkalinity and luminal acidification and generates the accumulation of viscous mucus, mainly in the lungs and gastrointestinal tract, which leads to organ dysfunction and cystic fibrosis disease manifestation." (PMID 39272186, 2024). "KB407, a modified HSV-1 vector, effectively carries two copies of the CFTR to respiratory cells in the lungs, providing a treatment option for all patients with cystic fibrosis, regardless of their specific genetic mutation." (PMID 39207577, 2024).
cystic fibrosis (continued). "Thus, the use of HD-Ad-CFTR combined with temporary immunosuppression shows promise for gene therapy for cystic fibrosis." (PMID 39596526, 2024). "For instance, cystic fibrosis, a genetic disease caused by mutations in the CFTR gene, leads to dysfunctional or absent CFTR proteins and accumulation of mucus in the lungs, resulting in persistent lung infections and progressive lung deterioration." (PMID 39207577, 2024). "Encouragingly, based on similarities between CFTR (ABCC7) — itself an ABC transporter protein and the causal gene for cystic fibrosis — and ABCA3, recent studies have repurposed drugs developed to modulate CFTR function for restoration of ABCA3 function in cancer cell line models." (PMID 38226623, 2024). "Moreover, NME1/2’s interaction with the CFTR (cystic fibrosis transmembrane conductance regulator) implicates their involvement in cystic fibrosis." (PMID 39063217, 2024). "The Greek, non-consanguineous couple at risk for cystic fibrosis showed the same pathogenetic variant in the exon 11 of CFTR gene NM_000492.4:c.1521_1523delCTT (Phe508del)." (PMID 38927598, 2024). "Their ability to increase CFTR function while reducing cellular stress and inflammation, together with their favorable safety profile and accessibility, makes them valuable additions to cystic fibrosis treatment options." (PMID 39043981, 2024). "The discrepancies observed, like the S912L CFTR mutation, between AlphaMissense predictions and studies on CFTR are not unexpected, especially when the mutations in question are part of complex alleles in cystic fibrosis or other diseases." (PMID 38744964, 2024). "The recently introduced CFTR modulators may be useful in decreasing the basal inflammatory status of people with cystic fibrosis, improving bone mass in these patients." (PMID 36979360, 2023). "Cystic fibrosis patients suffer from a lung disease characterized by excessive inflammation and chronic infection as well as a variety of other systemic anomalies associated with the consequences of abnormal cystic fibrosis transmembrane conductance regulator (CFTR) function." (PMID 37259368, 2023). "Identifying the mechanisms by which CDK8 and CDK19 affect expression of genes in the CFTR pathway may improve understanding the pathophysiology of cystic fibrosis, but will require further studies." (PMID 36545778, 2023). "Regarding secretory diarrhea, it has been proposed that they could be affected by a dysregulation in CFTR, mentioned in cystic fibrosis section." (PMID 37887299, 2023). "Besides its functional importance in cystic fibrosis, CFTR also represents a major chloride and hydrogen carbonate ion channel in the intestinal mucosa to control ion and pH homeostasis in the gut." (PMID 37569286, 2023). "Furthermore, cystic fibrosis drives intense research to identify novel drugs to modify CFTR activity, which also holds the potential to be utilized in the prevention of TIP." (PMID 36609875, 2023). "Inflammation may develop due to internal dysfunction of the cystic fibrosis transmembrane conductance regulator (CFTR) protein or external factors in patients with cystic fibrosis." (PMID 37324924, 2023). "Finally, we found that BCi-NS1.1-derived HAE cultures express functional CFTR channels, a characteristic important for the study of cystic fibrosis in this model." (PMID 37635251, 2023). "Moreover, a FIV-CFTR based vector pseudotyped with the GP64 protein restored CFTR activity in pigs with cystic fibrosis." (PMID 36992407, 2023). "In the context of cystic fibrosis, SRI-37240 (10 or 30 μM) could rescue CFTR function to a reasonable extend in cells stably expressing human CFTR cDNA containing the common G542X nonsense mutation." (PMID 37047074, 2023). "Indeed, structurally informed small molecule “correctors” that affect the biosynthesis and trafficking of mutant CFTR through the secretory pathway are now used to treat cystic fibrosis." (PMID 38161385, 2023).
cystic fibrosis (continued). "The most common cystic fibrosis mutant, CFTR ΔF508, is also degraded by the ERAD pathway." (PMID 37561577, 2023). "Loss of ATP8B1 function and downregulation of cystic fibrosis transmembrane conductance regulator (CFTR) in biliary cells can lead to impaired bile acid excretion and may contribute to the development of extrahepatic cystic fibrosis in PFIC1 patients." (PMID 37324459, 2023). "Cystic Fibrosis, a genetic disorder characterized by progressive lung disease, results from mutations in the gene encoding the cystic fibrosis transmembrane conductance regulator (CFTR) protein that disrupt anion transport in epithelia and other tissues throughout the body." (PMID 37568151, 2023). "Here, we investigated whether the REPAIRv2 base editor is also able to recover CFTR full-length expression in a different cell model of cystic fibrosis, like the human bronchial 16HBEW1282X cells." (PMID 37446121, 2023). "CF is a monogenic, autosomal recessive disorder with highly variable and complex clinical manifestations due to two mutations in the cystic fibrosis transmembrane conductance regulator (CFTR) gene that is situated on the long arm of chromosome 7 and contains 27 exons." (PMID 36678791, 2023). "We also demonstrate that both types of organoids can be used for functional assessment of the CFTR channel by the FIS assay, using the organoids from a healthy donor (wt/wt) and from two cystic fibrosis patients with homozygous F508del mutation of the CFTR gene (F508del/F508del)." (PMID 37047264, 2023). "Studies are needed to determine whether discontinuing maintenance therapy is safe in people with cystic fibrosis receiving CFTR modulators." (PMID 36631132, 2023). "BMMSC-EVs packaged with CFZF-VPR, a zinc finger activator, successfully activated cystic fibrosis transmembrane conductance regulator (CFTR) expression in target cells, suggesting that these engineered EVs can be used as an adjunctive cellular therapeutic approach to treat cystic fibrosis." (PMID 37221595, 2023). "Several reports have indicated that SARS-CoV-2 infection displays unexpected mild clinical manifestations in people with cystic fibrosis (pwCF), suggesting that CFTR expression and function may be involved in the SARS-CoV-2 life cycle." (PMID 36899912, 2023). "FDA-approved CFTR modulators, now widely used for patients with cystic fibrosis, may also help to reduce morbidity and mortality due to high-pathogenicity human coronaviruses." (PMID 36625656, 2023). "Cystic fibrosis is a monogenetic disease with mutations in the cystic fibrosis transmembrane conductance regulator (CFTR) gene leading to a paucity or absence of the chloride channel activity in epithelial cells." (PMID 37371177, 2023). "Cystic fibrosis transmembrane conductance regulator (CFTR) dysfunction leads to cystic fibrosis." (PMID 37108830, 2023). "Cystic fibrosis is an autosomal recessive disorder characterized by respiratory failure due to a vicious cycle of defective Cystic Fibrosis Transmembrane conductance Regulator (CFTR) function, chronic inflammation and recurrent bacterial and fungal infections." (PMID 38123809, 2023). "Cystic fibrosis has been a target for gene therapy since the cloning of the CFTR gene in 1989." (PMID 37896217, 2023). "In cystic fibrosis, the dysfunctional CFTR channel cannot influence water transport balance." (PMID 38132905, 2023). "The understanding of how CFTR modulator therapy impacts extrapulmonary manifestations of cystic fibrosis will have the upmost importance for better understanding the pathophysiology of these manifestations and the search for directed and effective therapeutics against them." (PMID 36979360, 2023). "In patients with cystic fibrosis, multiple gastrointestinal tract disorders and pancreatic insufficiency lead to maldigestion and malabsorption of nutrients as a consequence of the genetic defect in the CFTR protein." (PMID 38140272, 2023).